MIR487B (microRNA 487b)
Synonyms: hsa-mir-487b; MIRN487B; mir-487b
Gene: MicroRNA gene on chromosome 14 (101,046,455 to 101,046,538, forward strand). Ensembl gene ENSG00000207754.
Gene Ontology:
Biological process: miRNA-mediated post-transcriptional gene silencing
Cellular component: RISC complex
Homologues: Orthologues: chimpanzee ptr-mir-487b (100% identical), macaque mml-mir-487b (99% identical), pig MIR487B (87% identical), guinea pig MIR487B (86% identical), rat Mir487b (82% identical). Paralogues in human: MIR487A (70% identical), MIR494 (64% identical), MIR539 (64% identical), MIR1185-1 (63% identical), MIR154 (63% identical), MIR323A (63% identical), MIR1185-2 (61% identical), MIR323B (58% identical), MIR382 (58% identical), MIR496 (58% identical), MIR381 (56% identical), MIR409 (54% identical), and 4 more.